CDKN2A (cyclin dependent kinase inhibitor 2A)
Diseases named in the same sentence as CDKN2A in open-access papers (continued):
Sharing a sentence is not in itself a finding about the gene and the disease.
pancreatic cancer (continued). "Key mutations in oncogenes such as KRAS with deactivation of tumor suppressor genes SMAD4 and CDKN2A/INK4A have been implicated in the development and progression of pancreatic cancer." (PMID 26760962, 2016). "The overall methylation frequency of CDKN2A in blood, pancreatic tissue and juice for pancreatic carcinoma were more than that in normal controls, suggesting a potential role of CDKN2A methylation analysis in diagnosing pancreatic cancer." (PMID 26338139, 2015). "We observed that the frequency of CDKN2A methylation was significantly higher in pancreatic cancer patients than in normal healthy controls, the pooled OR = 17.19, 95% CI = 8.72–33.86, P < 0.00001." (PMID 26338139, 2015). "Combined survival data from all three studies showed OS tended to be shorter in pancreatic cancer patients with epigenetic abnormalities of CDKN2A than in PCs with normal expression of CDKN2A gene (OR = 4.46, 95% CI = 1.37–14.53, Z = 2.48, P = 0.01)." (PMID 26338139, 2015). "We observed that the frequency of CDKN2A methylation was significantly higher in pancreatic cancer patients than in normal healthy controls." (PMID 26338139, 2015). "It needs to be emphasized that the epigenetic alterations other than CDKN2A promoter hypermethylation also contribute to the development of pancreatic cancer." (PMID 26338139, 2015). "Familial pancreatic cancer is rare; it is associated with germline mutation in CDKN2A (cyclin-dependent kinase inhibitor 2A) and breast cancer gene 2 (BRCA2)." (PMID 25032044, 2014). "MTAP and CDKN2A are homozygously co-deleted, with a frequency of 35 to 70%, in lung and pancreatic cancer, glioblastoma, osteosarcoma, soft-tissue sarcoma, mesothelioma, and T-cell acute lymphoblastic leukemia." (PMID 19478948, 2009). "CDKN2A/p16 is located on chromosome 9p21.3 and represents one of the most frequently altered tumor suppressor loci in human malignancies, such as melanoma, glioblastoma, pancreatic carcinoma, and familial melanoma syndromes." (PMID 41596618, 2026). "Interestingly, CDKN2A‐inactivated pancreatic cancer exhibits increased sensitivity to paclitaxel and irinotecan, with paclitaxel in particular mimicking the effects of CDKN2A restoration." (PMID 41187942, 2025). "One example involves KRASG12D and CDKN2A deletions in pancreatic cancer." (PMID 40758706, 2025). "Both types of altered genotype, CDKN2A and CDK4, have a higher risk for pancreatic cancer." (PMID 38607041, 2024). "Similarly, CDKN2A is also one of the most common genetic changes in pancreatic cancer precursors, mainly manifested as deletion." (PMID 38573998, 2024). "The most commonly used active suppressor in pancreatic cancer is P16/CDKN2A." (PMID 39087024, 2024). "In non-Hispanic white pancreatic cancer patients, 0.6% had CDKN2A germline mutations, with higher rates in those with a family history, indicating its relevance in hereditary cases." (PMID 38666907, 2024).
pancreatic cancer (continued). "Personalized treatment approaches, especially considering CDKN2A status, could enhance the efficacy of clinical trials for advanced pancreatic cancer." (PMID 38666907, 2024). "In line with the previous screen, Cdkn2a was the top-scoring gene followed by Rnf43 and the newly identified genes, Usp15 and Scaf1, further supporting their function as strong suppressors of pancreatic cancer in KC mice." (PMID 38902237, 2024). "In addition, studies have found that pancreatic cancer tumor growth and proliferation are related to CDK2/4/6 activation caused by CDKN2A deletion, and CDKN2A is closely related to the malignancy of esophageal squamous cell carcinoma." (PMID 38206516, 2024). "Another syndrome with genetic changes that may favour the development of pancreatic cancer is familial atypical multiple melanoma syndrome (FAMMM), which in 38% of cases is caused by mutations in the P16INK4A/CDKN2A gene." (PMID 37509296, 2023). "In a prospective phase II clinical trial known as TAPUR, where 12 patients with pancreatic cancer and a variant mutation in the CDKN2A gene received Palbociclib monotherapy, no objective response was confirmed after 16 weeks." (PMID 38137564, 2023). "For instance, in pancreatic cancer cell lines, deletions in the CDKN2A and SMAD4 genes, both of which are common in pancreatic cancer tumors, have in addition to a direct consequence on the coding gene, a three-dimensional consequence altering the contact domains in the area." (PMID 37457299, 2023). "Besides, in the context of CDKN2A deletion, one of the abnormal signal nodes of pancreatic cancer is characterized by increased ability of HGFR and EGFR, and neuropilin 1, CD44 and β1 integrin get an increased expression." (PMID 36961395, 2023). "CDKN2A also played a vital role in regulating the anoikis in hepatocellular carcinoma cells and pancreatic cancer cells and hence could serve as an anoikis-related signature gene to predict the prognosis of endometrial carcinoma patients." (PMID 37350934, 2023). "CDKN2A methylation plays an essential role in the occurrence and development of pancreatic cancer, and it may become a prognostic marker of pancreatic cancer." (PMID 36117848, 2022). "The onco-suppressor gene P16/CDKN2A is inactivated in more than 90% of pancreatic cancer cases." (PMID 36556296, 2022). "Ten (58.8%) of the 17 CDKN2A VUSs identified in a study of 638 patients with familial pancreatic cancer were found to be functionally deleterious in our assay and could be reclassified as likely pathogenic variants." (PMID 35001868, 2022). "The RR of developing pancreatic cancer was reported as 13–39 for individuals with mutations in CDKN2A; however, there are no specific screening guidelines for FAMMM." (PMID 34476650, 2021).
pancreatic cancer (continued). "CDKN2A gene occurs more frequently in cell lines than in pancreatic cancer tissues." (PMID 35004697, 2021). "Pancreatic cancer samples exhibited high frequencies of KRAS (62.8%) and CDKN2A (17.2%) mutations." (PMID 33397889, 2021). "In addition, it has been reported that inactivation of SMAD family member 4 (SMAD4) and cyclin dependent kinase inhibitor 2A (CDKN2A) is related to the development of pancreatic cancer." (PMID 32587798, 2020). "Similarly, pancreatic cancer patients with CDKN2A deletion were prone to become therapy un-responsive." (PMID 32950968, 2020). "Of the other three genes, CDKN2A was previously shown to affect pancreatic cancer." (PMID 33144687, 2020). "Our results show no such correlation, which may be due to an almost universal inactivation of the CDKN2A gene in pancreatic cancer partly because of methylation." (PMID 31417657, 2019). "Moreover, another tumor suppressor gene on chromosome 9pP16, CDKN2A is inactivated in about 95% of pancreatic cancers." (PMID 28587243, 2017). "The exome sequencing of a large set of patients with familial pancreatic cancer demonstrated that inherited pancreatic cancer is highly heterogeneous: in these patients, germline mutations of ATM, BRCA2, CDKN2A and PALB2 are observed, all elevating risk of developing pancreatic cancer." (PMID 29156578, 2017). "As above stated, the CDKN2A locus is inactivated in >90% of pancreatic cancers." (PMID 29156578, 2017).
pancreatic cancer (continued). "Despite all the hints pointing towards an association between common genetic variability in the CDKN2A/B gene region and pancreatic cancer risk no one has attempted to directly relate them so far." (PMID 27486979, 2016). "The CDKN2A (p16) gene plays a key role in pancreatic cancer etiology." (PMID 27486979, 2016). "Only 3 of the 15 pancreatic cancer and CM families in this study had 3 cases of CM together with one case of pancreatic cancer, and in none of these families was a CDKN2A mutation identified." (PMID 25803691, 2015). "Improved understanding of the role of CDKN2A in pancreatic cancer may offer a tool to refine diagnosis and therapeutic management of pancreatic cancer patients." (PMID 26338139, 2015). "CDKN2A is aberrant in twenty-two percent of patients with pancreatic cancer." (PMID 25714017, 2015). "We screened tumors from 171 pancreatic cancer patients for mutations in KRAS and CDKN2A genes." (PMID 23565280, 2013). "Although the specific CDKN2A PV was not disclosed in this Australian study, most PVs described in the literature affect the p16INK4a protein, generally correlating with a 15–20% lifetime risk of pancreatic cancer." (PMID 38822936, 2024). "Whole genome sequencing of such familial pancreatic cancer (FPC) patients has recently elucidated the heterogeneous mutational landscape and outlined the importance of mutations in susceptibility genes like ATM, BRCA2, and CDKN2A (cyclin-dependent kinase inhibitor 2A)." (PMID 34680288, 2021). "Furthermore, 15% of pancreatic cancers show hypermethylation of the promoter sequence for CDKN2A." (PMID 31608239, 2019). "Moreover it has been shown that a small proportion of pancreatic tumors arises as a result of high penetrance germline mutations in genes such as BRCA1, BRCA2, p16/CDKN2A, STK11/LKB, ATM, PALB2, and DNA mismatch repair genes, usually in the context of familial cancer syndromes." (PMID 27486979, 2016). "Similarly, no CDKN2A mutations were seen in 3 individuals with isolated pancreatic cancer, and 6 individuals with pancreatic cancer and a first-degree relative with pancreatic cancer." (PMID 25803691, 2015). "Our results are not sufficient to exclude pancreatic cancer as part of the phenotype in Danish CDKN2A carriers and it is unknown if there is an increased risk of cancers other than CM." (PMID 25803691, 2015). "Previous studies demonstrated that the loss of function of CDKN2A is mainly caused by the hypermethylation of CDKN2A gene promoter; however, whether or not it is associated with the incidence of pancreatic cancer still remains unclear." (PMID 26338139, 2015). "It has not been possible to attribute pancreatic cancer to certain CDKN2A mutations yet." (PMID 24281082, 2010).
pancreatic cancer (continued). "The second highest co-occurring pair in the common gene projection, CDKN2A and KRAS, also majorly occurs in pancreatic cancer." (PMID 39040139, 2024). "We next investigated sympathetic innervation in the LSL-KrasG12D/+; Cdkn2a (Ink4a/Arf)lox/lox; Pdx1-Cre (KIC) mouse model of pancreatic cancer." (PMID 35418199, 2022). "The current findings indicate that AKT1, CDKN2A, ERBB2, and IL6 are the critical common hubs related to promoting both liver and pancreatic cancers." (PMID 35154607, 2021). "The current results indicate that AKT1, CDKN2A, ERBB2, and IL6 are the common protein core of liver and pancreatic cancers, and STAT3, CASP3, NOTCH1, and CTNNB1 are possible differential proteins that discriminate these cancers." (PMID 35154607, 2021). "AKT1, CDKN2A, ERBB2, and IL6 are common protein core of liver and pancreatic cancers, while STAT3, CASP3, NOTCH1, and CTNNB1 are possible differential proteins to discriminate these cancers." (PMID 35154607, 2021).